IL4 (interleukin 4)
Diseases named in the same sentence as IL4 in open-access papers (continued):
Sharing a sentence is not in itself a finding about the gene and the disease.
infection (continued). "In contrast to littermate control BALB/c mice, which developed ulcerating, necrotic lesions following infection with L. major LV39 and IL81, lack of IL-4-responsive CD4+ T cells led to a healing phenotype similar to that of the resistant C57BL/6 mice." (PMID 29176972, 2017). "It was observed that rTgHSP70 immunization did not alter the production of IL-2, IL-4, IL-6, IL-10, IL-17a, IFN-γ, nor TNF, although infection with T. gondii promotes the production of inflammatory cytokines IL-6, IFN-γ, and TNF in all groups of mice." (PMID 28487847, 2017). "BMDMs were first treated or not with ATRA during 3 days (concomitant with IL-4 and before stimulation with LPS) to address ATRA effects during the development of M1/M2 phenotypes, by mimicking stimuli from infection environment." (PMID 29204144, 2017). "First we demonstrated that HIV-1 SF162 (R5) or LAI (X4) infection did not influence the capacity of the Th-cells to produce IFN-γ, MIP-1β or IL-4." (PMID 26808476, 2016). "It is still not understood why despite Th2 cytokines such as IL-4 suppressing IL-17 and IL-23, IL-17-producing cells are still detected in AD and whether IL-17 contributes to AD initiation or represents an epiphenomenon of cutaneous colonization and infection with bacteria in AD." (PMID 26217343, 2015). "Infection also failed to stimulate the production of IL-10 by Foxp3+ Treg cells, despite increased IL-10 production by CD4+ Foxp3− IL-4+ Th2 cells." (PMID 26195548, 2015). "As the downstream targets of NF‐κB activation, we found that inflammatory cytokines IL‐2, IL‐4, IL‐6, TNF‐α, and IFN‐γ were significantly increased in the infected organoids compared to the organoids without any infection." (PMID 25214524, 2014). "None of the increases in IL-4, IL-5, IL-9, and IL-13 in response to SEA were correlated with pretreatment infection intensity." (PMID 24357629, 2014). "After primary infection, CD4+IL-4+ T cells disseminate around the body to lymphoid and nonlymphoid organs, such as airways, peritoneal cavity, and liver, and have a lower apoptotic potential." (PMID 23053394, 2012). "Conversely, infection of neonatal mice with the same weight-based dose of RSV resulted in an absence of IFNγ, coupled with increases in IL-4 and IL-10." (PMID 22792355, 2012). "HCs were pretreated with or without IL-10, TGF-β, IL-4, IL-6, IFN-γ, and TNF-α prior to infection with HIV-1BaL." (PMID 23217137, 2012). "At day 4 post-infection, we observed an increase in the proportion of splenocytes from rD7-vaccinated mice stimulated with the MHC class I/CD 8+ peptide that were producing IL-4 (p = 0.01; data not shown)." (PMID 23236530, 2012). "In our previous results we observed that praziquantel downregulated the IL-4, modulates IFN-γ production, and increased IL-10 production in spleen cells with 120 days of infection (data not shown)." (PMID 22623908, 2012). "In the absence of IL-4, normally resistant C57BL/6 mice develop patent infection, but the additional knock-out of IL-10 reverts mice back to a resistant phenotype." (PMID 18446236, 2008). "To investigate whether this reduction in GJB2 enhanced infection, we first silenced GJB2 in MDMs using RNA interference in the presence or absence of IL-4 treatment (20 or 50 ng/mL)." (PMID 40980890, 2025). "Interestingly, immunity conferred by LmexCen−/− was mediated mainly by a reduction in IL-4 and IL-10 levels rather than an increase in IFN-γ, thus enabling the control of infection and inhibiting disease development." (PMID 38543944, 2024). "Notably, in infected BALB/c mice, most LCMs clustered with LCMs from naive mice rather than with M(IL-4) LCM and exhibited less transcriptional change with infection than LCMs from C57BL/6 mice." (PMID 36948193, 2023).
infection (continued). "Related to IL-4, DHEA-reconstituted Gx mice in the absence of infection had decreased IL-4 concentrations, whereas, in infected mice, DHEA-reconstituted male Gx mice had higher IL-4 concentrations than females under the same conditions, resulting in a sex-dependent pattern." (PMID 37628731, 2023). "In addition, no significant alteration in the levels of IFNγ, IL-1β, IL-4, IL-6, IL-8, IL-10, CXCL10, and TNFα was observed in peripheral blood after Vir-S74-T3Bo infection by comparing Att-S74-T3Bo-inoculated and naïve control animals." (PMID 36466866, 2022). "For those plasma cytokines and chemokines with no sex-specific differences over the course of infection, a majority, including IL-2, IL-10, IFN-γ, MIP-1α, IL-3, IL-4, IL-5, IL-12p70, IL-13, IL-17, and G-CSF, exhibited differing temporal patterns between genotypes." (PMID 35970557, 2022). "There was no change in infection with M2 macrophages in IMM, but IL-4 alone increased infection." (PMID 36228018, 2022). "Infection of PBMCS with either CHIKV, DENV-1, -2, -3, and -4 did not produce detectable levels of IL-4, suggesting that PBMCs may not be the major source of IL-4 in the CHIKV and DENV-infected patients." (PMID 34215212, 2021). "The levels of IL-2, IL-4, IL10, and IL-17 were also not significantly altered by infection." (PMID 33815321, 2021). "However, this study also provided evidence for the importance of the Th2 response in acute schistosomiasis, with antigen-specific Th2 (IL-4, IL-5 and IL-13), but not Th1 (IFNγ), CD4+ T cells at week 4 post infection, significantly correlated to acute symptoms." (PMID 33953712, 2021). "Notably, we identified that infection with H. polygrus was able to suppress EAE in an IL-Rα-dependent manner, with further evidence to suggest that a lack of IL-4 signaling also ablates any disease protection mediated through the IL-33/ST2 receptor." (PMID 33117327, 2020). "Mannan, but not GalNac, inhibited IL-4/IL-13-dependent enhancement in pmacs, providing evidence that a mannose binding CLR such as SIGNR3 was responsible for the cytokine-dependent increase in infection." (PMID 31825972, 2019). "Similarly, at day 84 post-infection, no clear difference was observed in the concentration of IFN-γ, IL-1β, TNF-α, IL-12, IL-6, IL-10 and IL-4 in the both groups of mice." (PMID 31801478, 2019). "The crucial role of Th1 activation in the treatment of VL has been demonstrated previously by the role of IFN-γ in infection clearance; e.g., IFN-γ knockout mice failed to respond to an anti-IL-4 monoclonal antibody treatment, resulting in progressive infection." (PMID 31036692, 2019). "Furthermore, the transcriptomic analysis of lymph nodes in Zika virus-infected macaque monkeys revealed that IL-4 and NKT cell signatures, but not the Tfh cell signature, was strongly correlated with neutralizing antibody titer in the early phase of infection." (PMID 29928278, 2018). "The levels of IFN-γ, IL-4, IL-5, IL-6 and TNF-α were measured in the plasma of HP and non-HP PbNK65 1556Cl1-infected Hsd11b1Del/Del and WT mice at 21 to 24 days (HP) or 28 days (non-HP) after infection." (PMID 29062028, 2017). "Furthermore, using IL-4 reporter mice, we identified mast cells as the only skin cells transcribing but not producing IL-4 in C57BL/6 skin early in infection." (PMID 29067025, 2017). "In all infection models reviewed herein, disruption of ICOS signaling led to poor CD4+ T cell Th2 polarization and diminished IL-4 production, which may or may not have been due to reduced expansion of CD4+ T cells in all cases." (PMID 27559335, 2016). "In support of that hypothesis, we have previously shown that cross-linking of NK1.1 preferentially induces IFN-γ and no IL-4 production by CD1d-restricted NKT cells, suggesting a TCR-independent pathway of pro-inflammatory responses to infection." (PMID 24691125, 2014).
infection (continued). "Trends for increased IL-4/-13 and IL-10 production (n.s.)were detected in ileum as well as cecum tissue whereas IL-12, IFN-γ and TGF-β expression were detected at similar levels, irrespective of the infection status (data not shown)." (PMID 24040152, 2013). "Furthermore, at days 28 and 42 post infection, B6.CCR7-/- mice have a higher percentage of cells expressing IL-4, which was also seen in the CD4+ compartment but not by CD8+ T cells." (PMID 24205367, 2013). "No relevant IL-4 or IL-10 responses were found in the DLN, as the levels of these cytokines mRNA, in both non-immunized and BCG-immunized mice, were low and did not vary throughout the infection period." (PMID 22413022, 2012). "Natural infection with the whooping cough agent Bordetella pertussis also induces strong B. pertussis-antigen-specific IFN-γ responses in very young infants, with no detectable IL-13 or IL-4 production." (PMID 22550536, 2012). "To ensure that the infection protocol used induced significant levels of apoptosis, we infected THP-1 cells in the presence or absence of IL-4 at 10 ng/ml and monitored apoptosis and necrosis with a cell death ELISA kit, optimized to detect both apoptosis and necrosis." (PMID 21253484, 2011). "Note the smaller scales for the cytokines in panels A and B.)Levels tended to normalize to baseline values within 3–4 weeks of infection in all animals, with IL2, IL4, IL12p40, IFNγ, and CCL3 increasing again after 6 weeks of SHIV-RT infection of the naïve animals (not statistically significant)." (PMID 20011586, 2009). "Interestingly, in contrast to polarisation of BMDM with IL-4 prior to infection, treatment of non-polarised S.tm-infected BMDM with IL-4 resulted in improved infection control whereas stimulation with IFNγ led to an increase in intracellular bacterial numbers compared to unstimulated controls." (PMID 37190073, 2023). "Our previous finding that IL-4 and IL-13 drive the proliferative expansion of tissue-resident macrophages was made in L. sigmodontis-infected C57BL/6 mice, and although we appreciated that some of the proliferating cells had BM origins, we failed to observe monocyte recruitment during infection." (PMID 36948193, 2023). "However, there were no increases in IL-4, IL-10, IL-12p70 or IFN-γ, possibly due to the different VZV strains used (VZV Ellen strain in the previous report and the Gilden strain herein) or differential cell type specific responses to infection." (PMID 30786281, 2019). "Previous studies infecting global IL-4Rα−/−, IL-4−/−, and IL-13−/−mice on a BALB/c background with the visceralizing parasite Leishmania donovani have shown that the T helper 2 cytokines, IL-4, and IL-13, play influential but not completely overlapping roles in controlling primary infection." (PMID 31475014, 2019). "Furthermore, the levels of interleukin (IL)-2, IL-4, IL-6, IL-22, and interferon (IFN)-γ, but not that of tumor necrosis factor alpha (TNF-α), IL-10, and IL-9, increased to their highest levels at day 4 post-infection and decreased thereafter." (PMID 31711531, 2019). "Surprisingly, AZT treatment of LPS-treated IL-4 DCs or IFN-α DCs also reduced luciferase signals observed with the untreated DC subsets, suggesting that the viral transfer observed with these subsets relies on their productive infection and not on long term viral capture." (PMID 28426803, 2017). "Additionally, it should be noted that even during the early onset of infection with negative DTH response (III profile) IL-6 showed significantly higher serum levels than those of TNF-α, IL-4, and IL-10, suggesting that it exerts a latent immunopathogenic effect even during early infection onset." (PMID 27051668, 2016). "As initiating a Th1 immune response is critical for the control of Leishmania infection, we hypothesized that the mechanism through which NKT cells have a negative effect on the course of infection in C57BL/6 mice, could be through secretion of Th2 cytokines, in particular IL-4." (PMID 24967701, 2014).
infection (continued). "An observation that was consistent in DR1 and B10 mice after NC infection was that the pattern of secretion of IL-2, IFN-γ, and IL-4 was independent of epitope specificity or whether epitopes were major or minor in terms of the number of stimulated CD4 T cells." (PMID 22457834, 2012). "In addition, female IL-4 KO mice on a BALB/c background which, unlike males, can clear a high dose infection of T. muris (although delayed compared to wild-type mice) become susceptible after IL-13 neutralization, indicating a dominant role for IL-13 in immunity against T. muris." (PMID 23053395, 2012). "4-1BB ligation did not induce production of IL-4, a Th2 cytokine, IL-17, a cytokine which contribute to protection to MTB challenge and XCL-1, a chemokine released by suppressor CD8+ T cells during the chronic stage of infection with MTB that negatively affects production of IFN-γ by CD4+ T cells." (PMID 20544034, 2010). "At day 4 following CB4 infection of WT NOD mice, we observed significant increases compared to uninfected controls in the levels of both TNF-α and IL-6 and to a lesser extent IFN-γ Little to no production of IL-4, IL-5, IL-10, IL-12p70 was observed following infection (data not shown)." (PMID 19122812, 2009).
cancer (556 papers, 1991 to 2026). A tumor composed of atypical neoplastic, often pleomorphic cells that invade other tissues. "We aimed to compare the risk of cardiovascular disease and cancer between individuals starting systemic JAKi versus IL‐4/‐13 inhibitors (IL‐4/‐13i)." (PMID 40293104, 2026). "For example, mRNA encoding IL2RG, the gamma subunit common to the IL-2, IL-4, IL-7 and IL-21 receptors, is overexpressed by 155% in platelet-educated cancer cells." (PMID 40096084, 2025). "Cancer cell TAP2 protein downregulation was spatially associated with high local IL-4 mRNA expression." (PMID 40091029, 2025). "Our current data underline the importance of PARP14, not only in IL-4-induced M2 but also in cancer-cell-induced TAM polarization." (PMID 38612413, 2024). "Some studies associate higher levels of IL-4 with more advanced cancers, suggesting its potential as a prognostic marker." (PMID 39334861, 2024). "Excoriated pruritus can be an intolerable symptom in patients with cancer where Type 2 inflammation and its associated cytokines IL-4 and IL-13 play major roles in the pruritus." (PMID 38846700, 2024). "Mounting evidence indicates that C. sinensis infection drives Th2 immune responses and facilitates the production of the cytokines IL-13, TGF-β, IL-10 and IL-4, which have been implicated in promoting cancer stemness." (PMID 38285640, 2024). "Resistance of CSCs to traditional cancer treatments is associated with factors such as drug efflux proteins and proteins related to interleukin-4 (IL-4) signaling, as well as with the heightened activity of aldehyde dehydrogenase (ALDH)." (PMID 38067361, 2023). "High levels IL-4, IL-10, and IL-6 expression have been linked to the development of several cancer types, improved EMT, and the development of treatment resistance via the triggering of anti-apoptotic pathways and metastasis." (PMID 37941832, 2023). "Prior studies indicate that IL-4 and IL-10 polarize IgG4 class switching, and that IgG4 + B cells are increased in advanced cancer, and associate with poor patient survival and increased recurrence." (PMID 35255925, 2022). "Recently, the cytokines IL-6, IL-4 and alternatively activated macrophages that secrete norepinephrine have been implicated in mediating beige adipocyte formation during burn trauma, cancer, calorie restriction, and cold-induced WAT browning." (PMID 34423787, 2021). "Serum levels of IL-4 ≥ 431 pg/mL and IL-7 ≥ 54 pg/mL were associated with a 95% possibility of stage IV cancer." (PMID 33450900, 2021). "We found that interleukin-4 and interleukin-13 signaling pathways have discredited activity in cancer samples, and their associations have also been disrupted." (PMID 32832545, 2020). "IL-4 single nucleotide polymorphisms (SNPs) have also been explored for an association with susceptibility to cancer." (PMID 32744314, 2020). "Several previous studies have assessed the relationship between IL-4-590C/T gene polymorphism and smoking-related cancer in recent years; however, the results remain controversial." (PMID 31871935, 2019). "At present, there have been several case-control researches to explore the relationship between IL-4-590C/T (rs2243250) gene polymorphism and smoking-related cancer, but the results are still controversial." (PMID 31871935, 2019). "A significant relation was found for IL-4-590C/T gene polymorphism and the risk of smoking-related cancer in overall population (CT vs. TT: P=0.026, OR = 0.900, 95% CI: 0.820–0.987)." (PMID 31871935, 2019). "Our study indicates that smoking-related cancer susceptibility is associated with IL-4-590C/T polymorphism in the total population." (PMID 31871935, 2019). "A significant association between IL-4-590C/T variant and the susceptibility of the smoking-related cancer in Asian population (CT vs. TT: P=0.008, OR = 0.878, 95% CI: 0.798–0.967; CC + CT vs. TT: P=0.030, OR = 0.903, 95% CI: 0.824–0.990) was found." (PMID 31871935, 2019).